CRP (C-reactive protein)
Diseases named in the same sentence as CRP in open-access papers (continued):
Sharing a sentence is not in itself a finding about the gene and the disease.
Cognitive impairment (continued). "As increased CRP and NIC dependence have both been associated with cognitive impairment in SZ, it remains also to be determined if inflammation mediates the association between NIC dependence and cognitive impairment in SZ smokers." (PMID 30190688, 2018). "Our findings lend further credence to the notion that the relationships between CRP and cognitive impairments observed among individuals with psychiatric disorder, older adults, and individuals with underlying physical health problems are not merely epiphenomena." (PMID 28694011, 2017). "Elevated C-reactive protein (CRP), a non-specific biomarker of systemic bodily inflammation, has been associated with more pronounced cognitive impairments in adults with psychiatric disorders, particularly in the domains of memory and executive function." (PMID 28694011, 2017). "The differences in systemic inflammatory responses, including plasma C-reactive protein (CRP) and interleukin levels may also be responsible for increased susceptibility to OSA related cognitive deficits." (PMID 29194375, 2017). "We found that elevated serum levels of CRP were associated with increased risk of cognitive impairment in elderly and it was not mediated by presence of leukoaraiosis." (PMID 24587705, 2014). "We hypothesize that increased levels of the CRP biomarker would be related to brain leukoaraiosis, as evaluated by CT, and cognitive impairment." (PMID 24587705, 2014). "If CRP is elevated before measurable cognitive decline, inflammation may contribute to cognitive impairment or accelerate the deterioration." (PMID 23978069, 2013). "Patients with cognitive impairment (n = 377) and controls (n = 66) were examined by blood biochemistry tests, including ELISAs of serum CRP and RAGE, the Mini-mental State Examination (MMSE) and Montreal Cognitive Assessment (MoCA), and STEAM 1H-MRS of the left hippocampus and thalamus." (PMID 23978069, 2013). "Exploratory correlations with CRP and circulating lipids did not indicate substantial metabolic inflammation effects in controls or mild cognitive impairment (MCI), suggesting that the EOAD/ε4-linked CHI3L1 signal is not driven by general systemic inflammation." (PMID 41425914, 2025). "While CRP is an inexpensive and accessible marker of systemic inflammation, it cannot provide further insight about specific inflammatory pathways or mechanisms that might be related to cognitive impairment." (PMID 39354711, 2024). "Of importance, elevated levels of interleukin-6 (IL-6), C-reactive protein, and chitinase 3-like protein in cerebrospinal fluid of aged patients are positively correlated with their cognitive disorders, suggesting that chronic neuroinflammation takes part in cognitive impairment." (PMID 36932450, 2023). "Interestingly, neither CRP nor basophil percentage predicted anosognosia and associated cognitive impairment." (PMID 36128057, 2022). "Based on our findings, CRP may be used as a marker of cognitive impairment among older adults but may not be suitable for risk prediction for early cognitive decline." (PMID 33382815, 2020). "Findings suggest that levels of CRP at age 45+, are a marker of cognitive impairment but may not be suitable for risk prediction for cognitive decline." (PMID 33382815, 2020). "Similarly, significant working memory differences remained between elevated and normal CRP chronically ill patient groups after covarying for BMI, again suggesting that cognitive deficits associated with inflammation were not due to elevated BMI." (PMID 30364161, 2018). "However, it is important to note that in this cross-sectional study it is not possible to determine that CRP has a causal effect on cognitive impairment." (PMID 28694011, 2017). "Moreover, recent studies have established a correlation between serum CRP and cognitive impairment." (PMID 23978069, 2013).
Cognitive impairment (continued). "Increased levels of circulating C-reactive protein (CRP) have been correlated with changes in brain metabolites indicating early brain vulnerability, and serum CRP levels has also been shown to be elevated in patients with mild cognitive impairment, a prodromal stage of Alzheimer’s disease." (PMID 24223947, 2013). "These cognitive deficits are thought to be driven by chronic hypoxemia and impaired cerebral perfusion, systemic inflammation involving IL-6, TNF-α and CRP, and cardiovascular comorbidities frequently coexisting in COPD." (PMID 41598607, 2026). "Beyond well studied CRP, IL-6 and TNF-α, literature on other chemokines is sparser and mainly focus on clinically defined AD or mild cognitive impairment (MCI)." (PMID 39824904, 2025). "CRP and IBI were highest in the group with severe cognitive impairment, and the HALP score was highest in the group with mild cognitive impairment." (PMID 39398776, 2024). "One promising study analyzed fibrinogen and D-dimer compared to C-Reactive Protein (CRP) levels in more than 1830 hospitalized patients and found positive correlations between cognitive impairment and COVID-19 infection." (PMID 38500880, 2024). "Present study was to investigate hs-CRP concentration, brain structural alterations, and cognitive function in the context of AD [Subjective cognitive decline (SCD), mild cognitive impairment (MCI), and AD]." (PMID 37593375, 2023). "Higher DII scores, also known as larger inflammatory potential of the diet, have been related to increased levels of inflammatory biomarker including IL-6, CRP, and TNF-α, thus linking to cognitive impairment." (PMID 36688153, 2022). "A previous study suggested that the levels of CRP, TNF-α, IL-1β, IL-6, and IL-8 in the peripheral blood of patients with mild cognitive impairment (MCI) were higher than those in the normal population." (PMID 36590060, 2022). "A few studies have noted the importance of the C-reactive protein (CRP), a well-studied biomarker of systemic inflammation, to cognitive impairment." (PMID 32630059, 2020). "Single studies suggest the role of C-reactive protein (CRP), interleukin (IL)-1 receptor antagonist, IL-6, and tumor necrosis factor-α (TNF-α) with its receptors in the development of cognitive impairment in bipolar disorder as summarized in reviews." (PMID 30349492, 2018). "Serum CRP and RAGE were higher in the cognitive impairment group (CRP: 2.08 mg/L, range 1.07 − 3.36 mg/L vs. 0.21 mg/L, range 0.18 − 0.42 mg/L; RAGE: 4.01, range 2.49 − 5.71, vs. 2.28, range 1.84 − 3.03; P < 0.05 for both)." (PMID 23978069, 2013). "There is a significant difference in CRP concentration before and after targeted therapy between the group with no cognitive disorder and the group with cognitive disorder (P=.01 and P=.03, respectively)." (PMID 40966684, 2025). "Before targeted therapy, the group without cognitive disorder had a lower concentration of CRP, with a significant difference between the 2 groups." (PMID 40966684, 2025). "This inflammation can be reflected in markers such as white blood cell counts and C-reactive protein (CRP), which may affect brain structure, including cortical changes and reductions in gray matter volume, potentially contributing to cognitive impairment." (PMID 40700415, 2025). "Elevated levels of IL-6, TNF-α, and C-reactive protein (CRP) have been documented in individuals with LDs, suggesting that immune dysregulation may contribute to cognitive impairments." (PMID 40150106, 2025). "Elevated C-reactive protein (CRP), interleukin-6 (IL-6), and tumor necrosis factor-α (TNF-α) identify clinically relevant subgroups of patients characterized by greater severity, cognitive impairment, and poor treatment response." (PMID 41090786, 2025). "Patients with overall cognitive impairment at year 2 were more likely to have a high CRP level at baseline (n = 16, 30%) than patients without it (n = 18, 12%; p = 0.006)." (PMID 38840166, 2024).
Cognitive impairment (continued). "Patients with overall cognitive impairment at year 2 had higher CRP levels at baseline than those without it." (PMID 38840166, 2024). "Moreover, increased levels of interleukin-6 (IL-6) and C-reactive protein (CRP) have been observed in long sleepers, suggesting a link between prolonged sleep, inflammation, and cognitive impairment." (PMID 39839310, 2024). "According to the Standardized Mini Mental Test (SMMT) score, neutrophil count (p=0.001), CRP (p<0.001), and IBI (p<0.001) were significantly higher and lymphocyte count (p=0.001) and HALP score (p<0.001) were lower in the group with severe cognitive impairment." (PMID 39398776, 2024). "CSF CRP was found to be correlated with motor and non-motor severity in PD cases and also with mild cognitive impairment in AD individuals, with higher concentrations have been reported for bacterial, compared to viral, meningitis." (PMID 37873776, 2023). "This provides evidence that high fibrinogen or high D-dimer levels relative to CRP are not more commonly observed in people with pre-existing cognitive deficits." (PMID 37653345, 2023). "In most subdividing group analyses that included more than one study, the conclusion results suggested that patients with CD had higher CRP levels during the acute stroke period than did patients without cognitive impairment symptoms." (PMID 37509012, 2023). "A second dimension links raised D-dimer relative to CRP with subjective but not objective cognitive deficits and with evidence of occupational impact." (PMID 37653345, 2023). "Unlike all other markers, hs-CRP levels gradually increased with the aggravation of cognitive impairment, and there were significant differences among the three (P < 0.001) and between any two (all P < 0.05) groups." (PMID 35250538, 2022). "In our data, the correlation coefficients between SOD and cognitive score (MMSE, MoCA) were not high, and the differences in inflammatory indexes (ESR, CRP, IL-6) between patients with and without cognitive impairment were small." (PMID 35296032, 2022). "Our study suggests that elevated hs-CRP levels increase the odds of cognitive impairment in normal weight participants, but not in overweight participants." (PMID 33363509, 2020). "Studies examining the relationship between CRP and cognition among those without psychiatric disorders have typically focused on distinct sub-populations characterised by cognitive impairments." (PMID 28694011, 2017). "It suggests that the effects on the relationship between CRP and cognitive impairment are not completely mediated via leukoaraiosis." (PMID 24587705, 2014). "We found no interrelationship between the level of serum CRP and myo-inositol or other metabolites in the left hippocampus of hypertensives stratified by disease severity with or without cognitive impairment." (PMID 23978069, 2013). "Our findings supported our hypotheses; specifically, adolescents and young adults with MDD and severe suicidal symptoms had higher serum levels of proinflammatory cytokines (i.e., CRP and TNF-α) and exhibited greater cognitive deficits than did healthy controls." (PMID 38492052, 2024). "In addition, a recent study reported significantly higher levels of CRP in SVD patients with cognitive impairment (n = 40) compared to SVD patients without cognitive impairment (n = 38) and healthy controls (n = 35), respectively." (PMID 37685924, 2023). "In our data, serum SOD levels were significantly lower in patients with cognitive impairment in the early phase and at 3 months after mild AIS than in those without cognitive impairment, accompanied by increased systemic inflammation biomarkers (ESR, CRP, and IL-6)." (PMID 35296032, 2022). "However, some other researchers found that CRP was not an independent biomarker of cognitive impairment." (PMID 31138765, 2019).
Cognitive impairment (continued). "Concerning cognitive impairment, there was a negative relationship between MMSE score and CRP levels and a positive relationship between MMSE score and T3 levels." (PMID 37606393, 2023). "In patients with cognitive impairment, there were negative correlations between cognitive function (as measured by MMSE and MoCA) and both CRP and RAGE levels (P < 0.05)." (PMID 23978069, 2013).
acute coronary syndrome (238 papers, 2004 to 2026). Signs and symptoms related to acute ischemia of the myocardium secondary to coronary artery disease. "We have previously shown that current smoking and elevated CRP levels are associated with lower FAP concentrations in patients with acute coronary syndromes." (PMID 40690098, 2025). "CRP is also an established prognostic marker in acute coronary syndrome (ACS) and can also be a risk marker of perivascular disease (PVD)." (PMID 41497474, 2025). "In patients with acute coronary syndromes, elevated levels of IL-1ra, resistin, and CRP were independently associated with greater lesion complexity, functional significance, and plaque vulnerability." (PMID 41226718, 2025). "This study identified only a borderline association between post-procedural CRP and diastolic dysfunction severity after acute coronary syndromes." (PMID 41303851, 2025). "A rapid increase in C‐reactive protein (CRP) concentrations early in the development of acute coronary syndrome (ACS) is associated with worse outcomes and cardiac dysfunction." (PMID 38546019, 2024). "CRP value on admission shows the baseline inflammatory status of the subject, elevated CRP concentrations in patients with acute coronary syndromes being linked to more cardiovascular complications during follow-up." (PMID 38137807, 2023). "In patients with acute coronary syndromes, high CRP levels at admission are associated with poorer short- and long-term prognosis." (PMID 38137807, 2023). "These basic findings have been corroborated by a more recent clinical evaluation on patients with acute coronary syndrome (ACS) by reporting that higher UA levels are associated with higher C-reactive protein (CRP) and troponin values." (PMID 37760794, 2023). "For instance, in patients with acute coronary syndromes, serum sCD137 was positively linked with CRP." (PMID 38139346, 2023). "Two previous sub-analyses based on multicenter trials in acute coronary syndromes revealed that MCP-1 can be identified as an independent risk stratification biomarker in addition to C-reactive protein (CRP) and brain natriuretic peptide (BNP)." (PMID 36005444, 2022). "The VISTA-16 Trial suggested that a higher hs-CRP value was found to be associated with a poor prognosis after acute coronary syndromes (ACS) in 4,257 patients." (PMID 35282356, 2022). "Increased levels of IL-6 stimulate the liver to synthesize and secrete CRP, which functions as a pro-atherosclerotic factor and serves as a risk marker for mortality from acute coronary syndrome (ACS) after 30–90 days." (PMID 36294425, 2022). "In patients with STEMI, the elevation in the levels of highly sensitive C-reactive protein, a marker of systemic inflammation, is associated with an increased risk of all-cause mortality events in patients with acute coronary syndrome." (PMID 36200052, 2022). "The aim of this study was to evaluate the association between CRP elevation and coronary lesions severity as well as in-hospital mortality in patients presenting with acute coronary syndrome (ACS)." (PMID 34781995, 2021). "The mechanisms behind the CRP variants’ generation needs to be clarified to deal with various abnormalities such as acute coronary syndromes." (PMID 32992442, 2020). "It is seen that the advent of a high-sensitivity immunoassay of CRP allows the use of the risk predictive characteristic of its levels for evaluating CVD such as acute coronary syndromes." (PMID 32992442, 2020). "In another study on subjects with acute coronary syndrome undergoing percutaneous coronary intervention, higher CRP and lower serum albumin levels were significantly associated with contrast-induced nephropathy in univariate analyses." (PMID 31889082, 2019). "Increased plasma C-reactive protein (CRP) levels are associated with the occurrence and severity of acute coronary syndrome." (PMID 23950953, 2013).
acute coronary syndrome (continued). "Previous studies have shown that patients with acute coronary syndrome also have increased levels of serum CRP, which are positively associated with serum LCN2 levels even after adjusting for several confounders." (PMID 24359145, 2013). "Tumor necrosis factor (TNF)-α has been implicated in myocardial dysfunction resulting from acute coronary syndrome, and high levels of C-reactive protein (CRP) and interleukin (IL)-6 have been associated with subclinical ATS." (PMID 23029393, 2012). "In conclusion, leukocyte counts and levels of fibrinogen, CRP, myeloperoxidase, and pregnancy associated plasma protein-A were increased in patients with acute coronary syndromes." (PMID 21188207, 2010). "Previous reports have taken the view that elevated CRP levels are also associated with adverse outcomes in healthy individuals, as well as in patients with stable angina or acute coronary syndromes." (PMID 20512289, 2009). "Ongoing efforts are undertaken in an attempt to identify and validate additional cardiac biomarkers, for example, interleukin-6, soluble CD40L, and C-reactive protein, in order to further risk stratify patients with acute coronary syndrome." (PMID 19578513, 2008). "However, another study indicated that CRP was related to an increased risk of acute coronary syndrome in young women." (PMID 38074681, 2023). "CRP concentrations are associated with prognosis in CV diseases, acute coronary syndromes included." (PMID 38137807, 2023). "Furthermore, CRP is one of the common biomarkers associated with mortality in patients with acute coronary syndromes." (PMID 35300593, 2022). "Amit Kaura and colleagues investigate whether mildly elevated high sensitivity C-reactive protein is associated with mortality risk in patients with suspected acute coronary syndromes." (PMID 35192610, 2022). "In addition, the trend of increasing CRP after acute coronary syndrome is associated with cardiovascular and all-cause mortality." (PMID 34445853, 2021). "A study performed in patients with acute coronary syndrome has shown a strong association between CRP levels and resistance to FPC lysis, so acute-phase reactants could act as platelet aggregation and clot hardness markers." (PMID 33959088, 2021). "High CRP could reflect ongoing ventricular remodeling, as was also suggested previously for acute coronary syndromes, in which high CRP was associated with worsened mortality and left ventricular dysfunction." (PMID 30071583, 2018). "In acute coronary syndromes, the CRP inflammatory axis relates to the risk of death and may reflect myocardial injury." (PMID 23525424, 2013). "The aim of the present study was to evaluate leptin, pregnancy-associated plasma protein A (PAPP-A) and C-reactive protein (CRP) levels in patients with acute coronary syndrome and to assess their diagnostic efficacy in the identification of vulnerable plaques." (PMID 22836155, 2012). "Elevated CRP on admission is associated with poorer outcome in the acute coronary syndrome and among healthy individuals, but the relation of peak CRP concentration, during the course of AMI, to platelet reactivity and the risk of subsequent cardiovascular events has never been explored." (PMID 19583836, 2009). "This study investigated the association between the C-reactive protein-triglyceride-glucose (CTI) index and in-hospital major adverse cardiovascular events (MACE) in acute coronary syndrome patients after PCI treatment." (PMID 41607462, 2026). "In line with this, clinical studies have shown that increased CRP and proinflammatory remodeling of circulating leukocytes in patients with acute coronary syndrome (ACS) predicts the likelihood of recurrence of cardiovascular events." (PMID 41489606, 2026). "CRP represents a well-validated acute-phase marker correlated with myocardial injury severity and outcomes following acute coronary syndromes." (PMID 41458520, 2025).